INS (insulin)
Diseases named in the same sentence as INS in open-access papers (continued):
Sharing a sentence is not in itself a finding about the gene and the disease.
Insulin resistance (continued). "Insulin plays an essential role in the progression of NAFLD, however, the exact mechanisms underlying insulin resistance in NAFLD remain to be clearly defined." (PMID 29324774, 2018). "Obesity has been shown to result in the development of insulin resistance and impaired glucose tolerance, as well as increased insulin production from pancreatic cells." (PMID 30100880, 2018). "If this is insufficient to resolve the situation, chronic ER stress can lead to the induction of inflammatory pathways and insulin resistance, in part through Jnk activation and inhibition of insulin signal transduction." (PMID 29439143, 2018). "Among several major pathological changes that occur in type 2 diabetes, insulin resistance is the driving factor, which is characterized as a high blood glucose level, hyperinsulinemia and decreased insulin sensitivity." (PMID 29540751, 2018). "Insulin resistance was improved in all 3 groups, while insulin secretion declined in the NGT and IGT groups and was unchanged in the DM group." (PMID 29853879, 2018). "Insulin-mediated activation of Akt increases in 45% fat diet-induced obesity animal models, whereas activation is preserved or decreases in more severe insulin resistance models such as 60% fat diet-induced obesity animals or ob/ob mice." (PMID 30089498, 2018). "After four weeks on a pecan-rich diet, changes in subjects’ serum insulin, insulin resistance (HOMA-IR) and beta cell function (HOMA-β) were significantly greater than on the control diet (p = 0.024, p = 0.037, p = 0.021, respectively)." (PMID 29534487, 2018). "Insulin resistance was correlated with fasting levels of insulin and leptin/adiponectin (r = 0.913); of insulin, retinol binding protein 4 and leptin/adiponectin (r = 0.903); and of insulin, glycated albumin, and leptin/adiponectin (r = 0.913)." (PMID 29610560, 2018). "T2D is a complex and multifactorial disease that is characterized by impaired insulin secretion and insulin resistance." (PMID 29871606, 2018). "NAFLD has been recognized as the hepatic manifestation of MetS and insulin resistance, and it is characterized by a remarkable decreased insulin effects on both glucose and lipid metabolism." (PMID 30310390, 2018). "Adiponectin is the most important factor for increasing insulin sensitivity, while factors including leptin, resistin and C-reactive protein are known to be correlated with the increase of insulin resistance." (PMID 29793496, 2018). "Insulin, homeostatic model assessment-insulin resistance (HOMA-IR), FGF-23 levels, CIMT, left ventricular (LV) mass, LV mass index and myocardial performance index (MPI) were significantly higher in the GDM group." (PMID 30462803, 2018). "This condition is similar to ‘insulin resistance’, that the impairment of insulin receptor and signaling cascades was found with elevated serum insulin concentration." (PMID 30185439, 2018). "We focused our analyses on six commonly used OGTT-derived measures of insulin secretion and insulin resistance that were available." (PMID 28936587, 2018). "T2D is a chronic metabolic disease characterized by increased blood glucose levels (hyperglycemia) as a result of inadequate insulin secretion due to pancreatic beta (β)–cell dysfunction and insulin resistance." (PMID 29373500, 2018). "Previous studies have suggested that insulin resistance develops secondary to diminished fat oxidation and resultant accumulation of cytosolic lipid molecules that impair insulin signaling." (PMID 30524482, 2018). "Collectively, these results suggested that inhibition of autophagy by CQ further impaired mitochondria, reduced insulin-stimulated glucose uptake, and induced insulin resistance in the cells." (PMID 29552281, 2018). "Despite knowledge of increased oxidants in insulin-resistant humans and that scavenging mitochondrial oxidants benefits insulin sensitivity, the mechanism for increased oxidants in mitochondria in insulin resistance has remained unclear." (PMID 29402381, 2018).
Insulin resistance (continued). "Along the same line, septic animals displayed a reduced Kitt, which is indicative of insulin resistance, and both drugs improved insulin sensitivity." (PMID 29760586, 2018). "The findings demonstrate that GD can effectively alleviate glycaemia and insulin resistance and enhance insulin sensitivity in type 2 diabetic mice." (PMID 30337946, 2018). "All these results confirm the existence of CNS insulin resistance by showing the decreased response to intranasal administration of INS, which directly increases the levels of INS in the brain in overweight or obese subjects or those with type 2 diabetes." (PMID 30274197, 2018). "AngII desensitization of insulin signaling has been well established with multiple mechanisms characterized for angiotensin-induced insulin resistance." (PMID 30087656, 2018). "Hyperinsulinaemia led to insulin resistance, which was aggravated by a high-fat/high-sugar diet and weight gain, although beta cells maintained their insulin secretory capacity in response to glucose." (PMID 29497784, 2018). "Some metabolic syndrome features include impaired insulin signaling (insulin resistance), elevated systolic blood pressure, dyslipidemia, and increased adiposity." (PMID 29049981, 2018). "Our study, demonstrating that S. spinosum improved insulin sensitivity in two models of insulin resistance, supports the need to perform additional research in order to clarify the effects of this extract on other manifestations of the metabolic syndrome." (PMID 29768504, 2018). "Oxidative stress is closely linked with the development of T2DM and ROS can suppress the insulin response and contribute to the development of insulin resistance, a key pathological feature of T2DM." (PMID 29967664, 2018). "At skeletal muscle level, this lowers the insulin sensitivity, leading to hyperinsulinemia and insulin resistance on the long term." (PMID 30068918, 2018). "Differences in insulin, homeostasis model assessment of insulin resistance, triglyceride, free fatty acid, tumor necrosis factor-α and monocyte chemotactic protein-1 levels were statistically significant across the three groups (all P < 0.05)." (PMID 30355361, 2018). "Recently, insulin per se was demonstrated not to directly suppress SHBG in vivo, but rather the improvement of insulin resistance elevates SHBG after intensive insulin hypoglycemic therapy." (PMID 30057912, 2018). "During the aging process, chronic inflammation and mitochondria dysfunction in pancreatic β cells and insulin-sensitive organs have been demonstrated to be major mechanisms linking aging and insulin resistance." (PMID 30574122, 2018). "Previous studies have shown that there is a clear link between immune and insulin signaling in insulin resistance." (PMID 29760586, 2018). "HOMA-IR and HOMA-Beta is a mathematical method used to quantify insulin resistance and beta-cell function based on fasting insulin and glucose levels." (PMID 29543915, 2018). "LPS can activate pro-inflammatory cytokine production, leading to impaired insulin sensitivity and induction of insulin resistance-related metabolic disorders." (PMID 29507837, 2018). "Accordingly, a previous work reported that insulin stimulates cortical beta and theta activity and these effects are reduced in patients with insulin resistance." (PMID 29904337, 2018). "Treatment of C2C12 cells with METRNL markedly suppressed palmitate-induced insulin resistance, as detected by an impairment of insulin-stimulated IRS-1 and Akt phosphorylation." (PMID 30213948, 2018). "Protein kinase Cε (PKCε) is thought to mediate lipid-induced hepatic insulin resistance and the resulting impaired insulin-induced suppression of hepatic gluconeogenesis." (PMID 30036185, 2018). "Conversely, low serum amylase concentration is associated with an increased risk/prevalence of metabolic syndrome raised BMI, as well as insulin resistance and decreased plasma insulin concentrations even after adjusting for BMI52." (PMID 30293998, 2018).
Insulin resistance (continued). "Insulin resistance locally in the key insulin-responsive tissues, such as adipose tissue, liver, muscle, brain, immune cells and intestine cells, works alone or synergistically towards systemic insulin resistance." (PMID 30602666, 2018). "Insulin resistance was improved by butein treatment based on glucose tolerance and insulin tolerance tests." (PMID 30158592, 2018). "To understand the role of the gut microbiome and brain insulin resistance in these disorders, we evaluated behaviors and insulin action in brain of mice with diet-induced obesity (DIO) with and without antibiotic treatment." (PMID 29910467, 2018). "We attempt to explore the function of CARD9/MAPK pathway in diet‐induced insulin resistance, glucose tolerance impairment, insulin‐responsive organs and brown adipose inflammation." (PMID 29575791, 2018). "The reductions in both blood glucose and plasma insulin levels suggested that subchronic d-allulose treatment improved glucose tolerance at least partly by ameliorating insulin resistance in HFD-fed mice, consistent with previous findings." (PMID 29317623, 2018). "PPAR-γ decreases insulin resistance by regulating insulin sensitivity and promoting the synthesis of adiponectin." (PMID 30291215, 2018). "Insulin resistance has been reported as a combination of macrophages accumulation that secretes proinflammatory adipocytokines and altered outcome of insulin target cells." (PMID 30114249, 2018). "In conclusion, the skeletal muscle PC:PE ratio are elevated in conditions with insulin resistance, and reduced with increased insulin sensitivity." (PMID 29695812, 2018). "Our data is consistent with a model of botanical-mediated early pathway-selective insulin resistance in the liver characterized by a failure of insulin signaling to suppress glucose output." (PMID 30208938, 2018). "Previous studies have suggested that high fasting insulin levels drive insulin resistance in obesity." (PMID 30183740, 2018). "The chronically low grade of inflammatory responses not only causes pancreatic β-cells to be attacked but also reduces the liver and muscle sensitivity to insulin, which results in insulin resistance." (PMID 30687277, 2018). "Fasting glycated haemoglobin, glucose, insulin, and C-Reactive Protein (CRP) were measured and indices of metabolic risk were derived (homeostatic model of insulin resistance, HOMA-IR and metabolic risk z-score)." (PMID 28711418, 2018). "We note that combined treatment with insulin and hCG not only induced peripheral insulin resistance and hyperandrogenism, but also increased estrogen levels in female rats." (PMID 29719598, 2018). "Oral glucose tolerance test (OGTT), fasting serum insulin, and homeostasis model assessment of insulin resistance (HOMA-IR) were assessed to determine insulin sensitivity." (PMID 29593575, 2018). "In the present study serum adiponectin and leptin have been measured and their relationships with gender, age, BMI, waist circumference, fasting insulin, and insulin resistance have been considered in a West African population." (PMID 29890036, 2018). "HOMA-IR, which is based on fasting blood sample for insulin and glucose concentrations measured in a single blood sample, was used to calculate insulin resistance." (PMID 29975702, 2018). "Surrogate measures of insulin resistance including the overall fasting insulin (p = 0.010), endpoint HOMA-IR (p = 0.022), and oral glucose tolerance (p = 0.029) were improved in the coffee group." (PMID 30347674, 2018). "The skeletal muscle is the main tissue involved in insulin-stimulated glucose uptake, and its dysfunction is thought to be a primary contributor to insulin resistance." (PMID 30322152, 2018). "When insulin resistance increases due to obesity, inflammation, oxidative stress, aging, less physical activity, etc., insulin secretion is elevated to overcome insulin resistance and to maintain normoglycemia." (PMID 30041479, 2018).
Insulin resistance (continued). "ADCR and exercise both proved to be beneficial, but the combined intervention was most effective at inducing beneficial changes in body weight, body composition, glucose, insulin, insulin resistance and triglyceride in overweight and obese adults." (PMID 30219052, 2018). "A shift in the polarization of adipose tissue macrophages from an M2-like state to an M-like proinflammatory state resulting in insulin resistance favours inflammation and insulin resistance." (PMID 29507865, 2018). "Physical activity can reduce insulin levels and insulin resistance, thereby decreasing fasting glucose and total IGF-125." (PMID 30042430, 2018). "a continuous insulin elevation sustained over 120 min–indicated increased insulin resistance and impaired early insulin response." (PMID 29216249, 2017). "As a result of insulin resistance, the pancreas can lose its ability to produce insulin because of beta cell hyperactivity leading to dysfunction." (PMID 28294968, 2017). "High-fat feeding studies with rodents demonstrates that impairment of insulin action in the liver precedes the development of insulin resistance in other glucoregulatory tissues, including skeletal muscle and adipose tissue." (PMID 28329008, 2017). "An homeostatic model assessment of insulin resistance (HOMA-IR) like index served to assess insulin sensitivity with insulin resistance defined by values of 2.1 or higher." (PMID 28797289, 2017). "Insulin resistance, defined as impaired insulin action in insulin-responsive tissues (mainly skeletal muscle, liver and adipose tissue), precedes the development of hyperglycaemia by many years or decades." (PMID 28112007, 2017). "In order to evaluate the effects of ADSC transplantation on hyperglycemia and insulin resistance, the fasting blood glucose and insulin levels were measured." (PMID 29258603, 2017). "As an important factor in modulating insulin sensitivity, NEFAs can induce insulin resistance and impair β-cell function via PKC activation." (PMID 28935866, 2017). "It was reported that flavonoids and polyphenolic compounds can suppress insulin resistance, possibly mediated via activation of PPARγ, reduced oxidative stress, and enhanced glucose uptake and insulin sensitivity." (PMID 28529969, 2017). "Insulin resistance stimulates insulin release, reduces sex hormone-binding globulin production and increases free testosterone." (PMID 29387827, 2017). "This suggests potential impairment of insulin signaling and the development of insulin resistance and glucose intolerance." (PMID 28112248, 2017). "Posteriori analysis suggested that maternal serum insulin levels were higher in the NFCS than the other groups (p = 0.02), suggestive of hyperinsulinemia that is often associated with insulin resistance." (PMID 28820499, 2017). "The term “insulin resistance” is generally utilized to describe impaired insulin-mediated glucose uptake in skeletal muscle." (PMID 28587303, 2017). "In a previous report, miR-96 is found to be upregulated by SFA and involved in the suppression of insulin signaling intermediates, leading to insulin resistance in hepatocytes." (PMID 29124099, 2017). "A low-serum level of IGF-1 has been associated with insulin resistance, and treatment with recombinant IGF-1 has been shown to improve insulin sensitivity and glucose metabolism." (PMID 29422987, 2017). "Consistent with the results of our previous study, WMW repaired the impaired insulin signaling induced by palmitate and alleviated insulin resistance." (PMID 28928791, 2017). "The homeostasis model assessment of insulin resistance (HOMA-IR) using fasting insulin and glucose levels can be used to estimate insulin resistance." (PMID 28458728, 2017). "An important feature of this disease in the early stage are the physiological responses of β-cells as they adapt, via both enhanced function and increased morphological mass, to the increased insulin demand imposed by insulin resistance." (PMID 28168202, 2017).
Insulin resistance (continued). "Our previous studies have indicated that BPA exposure significantly affected insulin secretion and sensitivity, which contributed to peripheral insulin resistance in both offspring exposed perinatally to BPA and adult mice." (PMID 28790390, 2017). "Insulin resistance tightly relates with abnormal responses of the vascular endothelium, that is, endothelial dysfunction, to vasoactive molecules including insulin and the endogenous nucleoside adenosine." (PMID 29104874, 2017). "Having shown that maternal hyperinsulinemia is a potential factor driving the insulin resistance phenotype, we developed a regime of perigestational exercise to the mother aimed at improving her insulin sensitivity." (PMID 28291256, 2017). "Plasma levels of glucose, insulin, insulin resistance and lipid profiles of plasma, liver and kidney, adipocyte hormones and liver antioxidants were evaluated using standard kit methods." (PMID 29176994, 2017). "It’s not surprisingly to see that Creg1+/- mice with such an obvious obese phenotype showed exacerbated insulin resistance indicated by increased fasting glucose and insulin level, higher HOMA-IR scores, lager AUC of GTT and ITT." (PMID 28459882, 2017). "Dysregulation of insulin signaling often results in insulin resistance, the earliest feature in the pathogenesis of T2DM and metabolic disorders." (PMID 28912810, 2017). "GDM develops when β cells fail to maintain their pace with the increasing insulin resistance that occurs during the second half of pregnancy, and the resultant increased imbalance between insulin demand and supply is manifested in the rising glucose levels." (PMID 29292753, 2017). "Serum levels of sCD14 were positively associated with AST activity, active PAI-1 concentration and markers of insulin resistance (insulin and HOMA) in blood." (PMID 28880885, 2017). "In patients with renal impairment, insulin-mediated glucose metabolism is also reduced because of insulin resistance." (PMID 28235029, 2017). "In order to investigate further the role on testosterone on the glycaemic status in PCOS we conducted a regression analysis of fasting insulin levels and an index of insulin resistance (HOMA IR) adjusting for WC." (PMID 28546543, 2017). "Insulin resistance (IR) is a metabolic state in which insulin inefficiently regulates the tissue and cell for their uptake and utilization of glucose." (PMID 29164155, 2017). "In vivo assays showed that under insulin resistance of diabetes, phosphorylation level of Akt Ser473 decreases, and insulin signal transduction also significantly abates due to a decrease in insulin receptor concentration and kinase activity." (PMID 28333091, 2017). "The main abnormalityassociated with the syndrome is insulin resistance in peripheral tissues, whichmeans a low response to circulating insulin levels." (PMID 29340555, 2017). "Plasma glucose and insulin were tested during hunger state, and homeostasis model assessment of insulin resistance (HOMA-IR) was based on the blood samples." (PMID 28197123, 2017). "In time, however, the postprandial glucose levels and subsequently the FPG levels rises due to increased insulin resistance and failure of the β-cells to produce insulin, leading to overt T2DM." (PMID 28854264, 2017). "Insulin resistance is a pathological condition in which cells are normally suppressed to respond to insulin when needed." (PMID 29285009, 2017). "Age-related changes in muscle mass and composition can lead to insulin resistance with a reduced capacity for insulin-mediated glucose disposal." (PMID 29190709, 2017). "miR-29a is a conserved miRNA that acts as an oncogene, is highly expressed in breast cancer, and plays a major role in type 2 diabetes by participating in the insulin signaling pathway, as well as in insulin resistance." (PMID 28427228, 2017).